CRP (C-reactive protein)
Diseases named in the same sentence as CRP in open-access papers (continued):
Sharing a sentence is not in itself a finding about the gene and the disease.
appendicitis (continued). "Levels of CD64 were found to predict the occurrence of advanced appendicitis or PA; CRP levels and CD64 expression on leukocytes could better predict the diagnosis of CA." (PMID 35431963, 2022). "Thus, further studies need to be performed in different age ranges to assess if the extent of shared genetics of appendicitis and CRP varies with different age groups." (PMID 35693796, 2022). "Another study from India conducted on 65 patients found TLC not helpful for differentiating between appendicitis and negative appendicitis (AUC: 0.679) while associating CRP with AUC of 0.716 at cut off 8.76 mg/dL." (PMID 35495380, 2022). "CRP concentrations in serum of appendicitis patients (n = 325) were measured." (PMID 35693796, 2022). "With this multivariate analysis, both CRP and ratio between neutrophils and lymphocytes appear to be potential predictors of complicated appendicitis because they present statistically significant values (both with p < 0.0001), in contrast to leukocytes (p = 0.005)." (PMID 35106154, 2022). "When all predictors of the basic model were negative, the predicted risk of appendicitis was 0.002; adding CRP in this context increased the risk of appendicitis to 0.05 for a CRP value of 100 mg/L." (PMID 35535699, 2022). "Therefore, only CRP proved to be a good predictor of complicated acute appendicitis, in contrast to the other inflammatory parameters." (PMID 35106154, 2022). "In the diagnosis of appendicitis, complete blood count, C-reactive protein and abdominal ultrasound are the most commonly used diagnostic tools, while appendicitis scores are not widely used (25% of surgeons)." (PMID 36556939, 2022). "The diagnostic value of C-reactive protein (CRP) for appendicitis in children has not been evaluated in primary care." (PMID 35535699, 2022). "However, the Dutch guideline still advises against CRP-testing for children with suspected appendicitis." (PMID 35535699, 2022). "•C-reactive protein shows to be a good predictor of complicated acute appendicitis." (PMID 35106154, 2022). "Although no previous study has separately evaluated the value of adding CRP to other appendicitis features, we note that it was selected for use as a predictor in the Appendicitis Inflammatory Response score in secondary care based on logistic regression analysis." (PMID 35535699, 2022). "Furthermore, raised blood bilirubin has been demonstrated to be a possible marker for perforated appendix but lacked sufficient sensitivity and specificity, with elevated CRP superior to bilirubin in predicting perforated appendicitis." (PMID 36185898, 2022). "C-reactive protein (CRP) is an important biomarker in the diagnosis of acute appendicitis." (PMID 35693796, 2022). "CRP was the second most frequently reported test (38 studies, 9934 patients (4201 appendicitis)." (PMID 36328382, 2022). "In conclusion, adding CRP to symptoms and signs may help GPs decide whether to refer a child with suspected appendicitis to secondary care." (PMID 35535699, 2022). "In addition, the accuracy of the combination of leukocytes and C-reactive protein (CRP) for the diagnosis of acute appendicitis can be improved by increasing serum hepcidin levels." (PMID 35431963, 2022). "We propose that CRP may be a useful factor in predicting complicated appendicitis when supported by clinical findings and imaging, and look forward to further research of this factor." (PMID 34314464, 2021). "However, in complicated appendicitis, the CRP value was found to be higher than in simple appendicitis cases." (PMID 33936912, 2021). "The ease of application of the score, the sound construction, grading of parameters, avoiding of subjective parameters, and the introduction of CRP into scoring all make the appendicitis inflammatory response score into an attractive clinical prediction rule with higher specificity." (PMID 34295969, 2021). "Subacute appendicitis cannot be detected by CRP, IL-6 or leukocytes." (PMID 34064691, 2021).
appendicitis (continued). "Levels of CLR, CRP, sodium, and Tzanakis score might support decision-making regarding treatment options for pediatric appendicitis." (PMID 34222491, 2021). "In addition to clinical examination, laboratory tests such as white blood cell (WBC) count or C-reactive protein (CRP) are widely used as a next step in diagnosing acute appendicitis." (PMID 33851877, 2021). "In addition, the CRP values ​​were statistically significantly higher in the complicated appendicitis group compared to the simple appendicitis group." (PMID 33936912, 2021). "Specifically, high serum levels of CRP may be a useful factor in predicting complicated appendicitis prior to surgery when supported by clinical findings and imaging; however, further research is needed." (PMID 34314464, 2021). "CRP also has a variable role in the literature when it comes to appendicitis." (PMID 33133811, 2020). "Furthermore, in some publications, measurements of CRP and/or WBC revealed additional diagnostic value regarding the severity of appendicitis (e.g., advanced and perforated), whereas some publications negate such correlations." (PMID 33313029, 2020). "The upper normal limit of CRP at 0.5 mg/dl, set in accordance with hospital laboratory standards, could predict uncomplicated appendicitis with a specificity of 0.853 (sensitivity 0.326)." (PMID 33060696, 2020). "Preoperative high WBC count and CRP level and peritonitis indicated severe appendicitis." (PMID 33296384, 2020). "Similarly, Shakhatreh found a CRP sensitivity of 95.5% in 85 of 89 patients with histologically proven appendicitis." (PMID 32070390, 2020). "Hence, the preoperative CRP level can better reflect the high possibility of complicated appendicitis compared with the preoperative WBC count." (PMID 33296384, 2020). "According to some studies, a high CRP value in elderly patients with acute appendicitis, could be a suspect index for the existence of a perforation (AUC 0.811 with the cut-off of 101.9 mg/l)." (PMID 32156296, 2020). "Also, many studies have independently shown the importance of C-reactive protein(CRP) in the assessment of patients with appendicitis." (PMID 33024555, 2020). "High WBC, CRP and percentage neutrophils could indicate a higher possibility of severe appendicitis." (PMID 33060696, 2020). "CRP has been reported to be useful in the diagnosis of appendicitis; however, it lacks specificity." (PMID 32070390, 2020). "A CT scan should be considered in children with suspected acute appendicitis if they have vomiting, high CRP, and high WBC count, despite negative or non-diagnostic US results." (PMID 32899032, 2020). "In two recent publications including the herein reported 590 patients we analyzed possible constitutive differences between complicated and uncomplicated appendicitis with regard to cellular subpopulations in white blood cell counts and CRP: Significant and time stable differences were found." (PMID 31553729, 2019). "However, in our study, both WBC and CRP levels were within reference ranges in nine of 208 appendicitis patients." (PMID 31183274, 2019). "The percentage of CRP positivity was higher in the appendicitis group (51.9% vs 15%; p<0.05)." (PMID 29552432, 2018). "The utility of CRP in diagnosing appendicitis has been evaluated in many studies." (PMID 29552432, 2018). "The aim of this study is to test the diagnostic value of baseline and early change of C-reactive protein (CRP) concentrations, evaluated separately or in combination with the modified Alvarado score (MAS), in patients with clinically suspected acute appendicitis." (PMID 29793425, 2018). "CRP concentrations were higher in patients with acute appendicitis." (PMID 29793425, 2018). "WBC count and preoperative elevated CRP levels can aid the diagnosis of acute appendicitis." (PMID 29029533, 2017).
appendicitis (continued). "To better identify preoperative predictive factors of complicated appendicitis, we conducted a retrospective and a prospective study to determine the validity of three potential factors (body temperature ≥37.4 °C, CRP ≥4.7 mg/dl, and fluid collection surrounding the appendix on CT)." (PMID 27708690, 2016). "Our previous retrospective study revealed the three preoperative predictors of complicated appendicitis (perforated or gangrenous appendicitis), which are body temperature ≥37.4 °C, C-reactive protein ≥4.7 mg/dl, and fluid collection surrounding the appendix on computed tomography." (PMID 27708690, 2016). "INR and CRP increased significantly in patients with complicated appendicitis." (PMID 27330547, 2016). "Secondary aim was to examine if integration of US with PAS and CRP could be used to exclude the diagnosis of appendicitis with high safety in a substantial number of patients." (PMID 28044133, 2016). "The present study shows serum CRP is a good predictor of complicated appendicitis." (PMID 26859663, 2016). "However, in our study among patients whose WBC and CRP levels were within normal limits, diagnoses of AA (n = 5/199; 2.51%) and complicated appendicitis (1/79; 1.26%) have been made in respective number of patients." (PMID 27274988, 2016). "However, the predictive value of serum DNI for complicated appendicitis was only fair (AUC 0.738) and lower than that of serum CRP." (PMID 26859663, 2016). "The objective of this retrospective study is to determine NPV, PPV, and LR by using ROC curves estimated based on the most sensitive and specific cut-off values of WBC and CRP in their individual and combined uses in diagnosing or excluding acute and complicated appendicitis in pediatric patients." (PMID 27274988, 2016). "Similarly, our study has disclosed a significant increase in CRP in appendicitis progressed to perforation." (PMID 27642237, 2016). "Also, the presence of leucocytosis and an elevated C-reactive protein have been shown to correlate with acute appendicitis and its severity." (PMID 25956068, 2015). "One limitation of this study was that it was a retrospective one, so that we were unable to collect some significant data which could possibly have affected the outcomes, such as patient race, economic status, type of appendicitis, and CRP level." (PMID 26380377, 2015). "Based on these findings, it can be suggested that leukocyte count and CRP levels may be superior to MPV in diagnosis acute appendicitis." (PMID 24693387, 2013). "However, our study revealed that the sensitivity and specificity of leukocyte count and CRP were superior to those of MPV in diagnosis of acute appendicitis." (PMID 24693387, 2013). "Finally, an elevated NLR has been suggested as an adjunct to clinical evaluation in the diagnosis of acute appendicitis, with a better prognostic value than C-reactive protein or white blood cell count." (PMID 24098587, 2013). "However, we detected that the sensitivity and specificity of leukocyte count and CRP were superior to those of MPV in the diagnosis of acute appendicitis." (PMID 24693387, 2013). "The serum CRP levels were normal in 22 patients with acute appendicitis." (PMID 22866907, 2012). "There are in use different clinical classification for the acute appendicitis, but, since the correlation of CRP values with histopathology findings were studied, we used the classification that combines the gross appearance of the appendix with pathologic stage." (PMID 22866907, 2012). "Also, the score does not incorporate C-reactive protein as a variable, although many studies have shown the importance of C-reactive protein in the assessment of patients with appendicitis." (PMID 22447205, 2012). "In other cases the laboratory results might be supportive for a clinical decision, like the CRP result to decide if a patient suspected of bacterial infection should start antibiotic treatment or a patient, suspected for acute appendicitis should be operated." (PMID 21906396, 2011).
appendicitis (continued). "When all the three parameters were combined (TLC, CRP and percentage of neutrophil count), of the 92 patients positive for appendicitis (Groups B and C), 81 patients had all the three values raised and only 11 patients had one or more values in the normal range." (PMID 19568576, 2009). "Similarly, the present study has revealed a significant increase in CRP in appendicitis progressed to perforation." (PMID 16759345, 2006). "Measurement of IL-6 or CRP but not WBC had additional diagnostic value on the diagnosis of advanced or perforated appendicitis (groups 3 and 4)." (PMID 17132173, 2006). "Also, the level of CRP was significantly higher in a group with complicated appendicitis." (PMID 41470162, 2025). "However, both studies treated CRP as a categorical variable and simply identified it as a risk factor for prolonged hospitalization following appendicitis without providing a quantitative analysis of this association." (PMID 39726534, 2024). "This nomogram, incorporating variables such as Age, neutrophil-to-lymphocyte ratio, C-reactive protein level, operative time, appendiceal fecalith, and drainage tube, offers a convenient method for assessing the duration of hospitalization in pediatric patients with appendicitis." (PMID 39735250, 2024). "Similarly to previous studies, our data show that the combination of appendicoliths, CRP levels, ASA score, and BMI is highly predictive for advanced stages of disease such as gangrenous or perforated appendicitis with appendicoliths being the strongest risk factor." (PMID 39064205, 2024). "This study represents a significant contribution to the foundation of laboratory diagnosis for acute appendicitis, suggesting that, in conjunction with other analyses, these inflammatory parameters may ultimately replace other markers such as C-reactive protein (CRP)." (PMID 39767138, 2024). "Findings indicated that factors such as age, neutrophil-to-lymphocyte ratio, C-reactive protein levels, operative duration, presence of appendiceal fecalith, and use of a drainage tube were significantly associated with prolonged LOS following laparoscopic appendectomy in children with appendicitis." (PMID 39735250, 2024). "Similarly, while CRP per se did not qualify as a diagnostic tool in our study, the CRP to Albumin ratio is significantly and independently associated with severity of appendicitis." (PMID 36707812, 2023). "In other words, low lymphocyte count and CRP/Albumin can be used as markers to select those patients with acute right iliac fossa pain who would benefit from an operation of appendicectomy, i.e. those with gangrenous appendicitis, among those who have a clinical diagnosis of acute appendicitis." (PMID 36707812, 2023). "Elevation of CRP baseline concentrations mirrors inflammatory responses in the acute setting; it is indeed broadly acknowledged that increased CRP levels are encountered in patients with appendicitis, pancreatitis, cholecystitis, meningitis and, interestingly, in hemorrhagic stroke." (PMID 37158450, 2023). "Importantly, CRP is known as a potential biomarker for acute appendicitis and its severity in children, yet a study revealed that HLX and CTSB genes are possible etiologies for appendicitis and propose a shared genetic mechanism between appendicitis and CRP levels." (PMID 37873776, 2023). "Finally, we did not analyse the diagnostic value of CRP for outcomes other than appendicitis, so our conclusions are limited to appendicitis." (PMID 35535699, 2022). "Therefore, it is essential to develop prospective studies in order to confirm the possibility of diagnosing or even excluding a complicated acute appendicitis through determination of certain values of C-reactive protein, or even other analytical or clinical parameters." (PMID 35106154, 2022).
appendicitis (continued). "However, one must exercise caution as a very small group of young, normally fit patients, especially men, have been anecdotally found to present with normal levels of WBC and/or CRP and yet were confirmed to have acute appendicitis at surgery and/or by histopathology." (PMID 35223267, 2022). "A study from Taiwan had used different cut off values of CRP on the first 3 days after the onset of symptoms and concluded that serial measurements may serve as a useful predictive parameter in the early diagnosis of perforated appendicitis." (PMID 35495380, 2022). "We conclude from our data that C-reactive protein seems to be an independent predictor of complicated acute appendicitis and, therefore, when its measurement is above 63.3 mg/L, an early approach should be considered due to the high probability of complicated appendicitis." (PMID 35106154, 2022). "In order to identify preoperative predictive factors that may help to distinguish the severity of acute appendicitis, a retrospective study to determine the validity of three potential factors was conducted (leukocytes, C-reactive protein and ratio between neutrophils and lymphocytes)." (PMID 35106154, 2022). "CRP may be one useful indicator of complicated appendicitis due to simplicity and objectivity." (PMID 34314464, 2021). "Another scoring system is the appendicitis inflammatory response (AIR), which uses clinical criteria such as vomiting, fever, and pain intensity in the right iliac fossa (RIF) associated with leukocyte count and C-reactive protein (CRP) level to quantify the intensity of the inflammatory response." (PMID 33520210, 2021). "Moreover, it has been revealed that serum CRP levels will increase over time in appendicitis, raising question as to whether high CRP levels are more relevant to ARCD than to AA if confounding time factors related to CRP increase are not removed." (PMID 32953179, 2020). "Recently, the new Pediatric Appendicitis Laboratory Score (PALabS) including clinical signs, leucocyte and neutrophil counts, CRP, and calprotectin levels has been shown to accurately predict which children are at low risk of AA and could be safely managed with close observation." (PMID 32295644, 2020). "The combination of sB7H3 and CRP might improve the prediction of perforated appendicitis." (PMID 32953890, 2020). "Our primary objective was to compare levels of individual inflammatory protein mediators previously associated with intra-abdominal inflammation (CRP, PCT, interleukin-6 (IL-6), IL-8, IL-10, and monocyte chemoattractant protein-1 (MCP-1), SAA) in a cohort of children with suspected appendicitis." (PMID 30918467, 2019). "High WBC and CRP levels in a case with appendicitis may suggest perforation." (PMID 31547519, 2019). "The purpose of this study was to investigate the diagnostic performance of initial serum CRP measurement at admission and its early variation, evaluated both separately and in combination to the MAS in patients presenting to the ED with clinically suspected appendicitis." (PMID 29793425, 2018). "White blood cell (WBC) count, proportion of neutrophils, and C-reactive protein concentrations were higher and rebound tenderness, positive psoas sign, Rovsing sign, and heel drop test were significantly more common in patients with acute appendicitis than in those with other diagnoses." (PMID 27723842, 2016). "Maybe it would have been more suitable to ask for normal CRP and leukocyte counts, that usually may exclude appendicitis, (if not measured too early) in the cause of the disease." (PMID 26032861, 2015). "Mean values of the CRP in simple acute appendicitis (Group-B) were significantly greater than in normal appendix (Group A) (p <0.001), and also in complicated acute appendicitis (Group C) the CRP is significantly greater than in normal appendix and uncomplicated acute appendicitis (p <0.0001)." (PMID 22866907, 2012).